MLANA (melan-A)
Diseases named in the same sentence as MLANA in open-access papers (continued):
Sharing a sentence is not in itself a finding about the gene and the disease.
tumor (continued). "In immunohistochemical staining, the tumor cells were found to be positive for HMB45, Melan-A, and α-SMA, but negative for CD34, Desmin, c-kit, and s-100." (PMID 29921303, 2018). "Although the tumour cells showed an absence of melanocytic differentiation, as demonstrated by the lack of expression of markers such as HMB-45 and Melan-A, FISH analysis showed EWS gene rearrangement." (PMID 28086809, 2017). "Immunohistochemical (IHC) staining of the patient’s tumour revealed only focal SMA positivity, whereas the tumour was negative for Desmin, Caldesmon, S100, CD34, EMA, Melan A, and Pan-CK." (PMID 28304377, 2017). "The tumor cells were negative for CD21, CD23, CD35 and CD1a, CKpan, cam5.2, EMA, HMB45, Melan A, CD3, CD20, Desmin, SMA, and so on." (PMID 28386111, 2017). "C-KIT, necrosis, mitoses number, Melan A, HMB-45, S100 or tumour size had no statistically significant impact on mortality or recurrences (p>0.05)." (PMID 28443572, 2017). "The tumor cells were, as previously, negative for BerEP4, CK20, CK5/6, P63, HMB45 and melan A, but surprisingly CK AE1/AE3 was now negative and S100 strongly positive in all tumor cells." (PMID 28343447, 2017). "Immunohistochemistry revealed that tumor cells were positive for HMB45 and SMA, but negative for PAN-CK, desmin, S-100, melan-A, EMA, c-kit, and CD10." (PMID 28270196, 2017). "Immunohistochemically, the tumour was positive for human melanoma black 45 (HMB-45) and vimentin but negative for S-100 and Melan-A." (PMID 28086809, 2017). "Immunohistochemically, tumor cells were positive for CD34 and HHF-35, but negative for cytokeratin, HMB-45 and Melan-A." (PMID 26754205, 2016). "The immunophenotype (AE1/AE3-, vimentin+, PAX8-, alpha-inhibin+, Melan-A+, synaptophysin+ and NSE+) did not support a renal origin of the tumor." (PMID 27094262, 2016). "By contrast, the tumor cells were negative for HMB45 and Melan-A, which are markers of melanocytic differentiation." (PMID 25364450, 2014). "On immunohistochemistry, the tumor cells are typically negative for epithelial markers (i.e., EMA and cytokeratins), chromogranin A, synaptophysin, S-100, HMB45, and Melan-A." (PMID 25587475, 2014). "Immunohistochemically, the tumor cells were positive for S-100 protein, vimentin and BCL-2, and negative for HMB45, Melan-A, CD117, CD34 and CD99." (PMID 25364450, 2014). "Immunohistochemical stains were performed and demonstrated that the tumor nodule was negative for pan-cytokeratin and positive for S–100, HMB 45, and Melan-A." (PMID 24220097, 2013). "Immunohistochemically, tumor cells were positive for SMA, HMB45, and Melan-A and negative for CD10, RCC, CD45, CD117, CD34, EMA, and Desmin." (PMID 22953133, 2012). "Immunohistochemical staining revealed the tumor cells to be positive for HMB45, S100, and Melan-A but negative for cytokeratin (AE1/AE3) and epithelial membrane antigen." (PMID 23170958, 2012). "In the immunochemistry, Inhibine, CD99, EMA, chromogranin, synaptophysin were negative; the tumour cells strongly expressed PS100 and Melan A HMB45 was observed in some cells suggesting the diagnosis of metastatic ovarian amelanic melanoma." (PMID 21682901, 2011). "In this regard too, the present tumor had a unique immunoprofile, as S-100, HMB45 and Melan-A were all negative in both the core needle and incisional biopsies." (PMID 20598147, 2010). "The tumor exhibits positivity for Vimentin, PR, and SMA, with negativity for PanCk, S100, Desmin, PSA, CK5/6, BCL2, MDM2, and Melan A. Additionally, the Ki-67 proliferation index is approximately 25 %, and CD34 highlights only the vascular walls without tumor cell positivity." (PMID 40686513, 2025). "Importantly, BAPN treatment did not affect the expression of melanocytic lineage marker Melan-A, suggesting that ECM softening did not alter tumor cell identity." (PMID 41533929, 2025).
tumor (continued). "Notably, the patient in this case report was originally positive for Melan-A, HMB-45, and S100 in the left adrenal gland; however, when his tumour was excised approximately 2.5 years later, it was found no longer reactive for these markers." (PMID 39228985, 2024). "Immunohistochemical analysis confirmed the positive expression of pankeratin, PAX8 and RCC in the tumour cells while showing negative results for SOX10, HMB45 and Melan A. A notably elevated proliferative index, as indicated by Ki‐67 labelling, was observed within the tumour." (PMID 39355743, 2024). "The tumor did not reveal any specific differentiation (immunohistochemical stains showed that the tumor cells were negative for pancytokeratin, SMA, desmin, CD117, DOG1, CD34S100, Melan-A, and HMB45)." (PMID 35001360, 2022). "Tumor cells of case No. 2 were positive for AE1/AE3, CK7, calretinin, D2-40, focal positive for WT-1, and negative for HMB45, Melan-A, Desmin, S100, Syn, CgA, CD31, and CD34." (PMID 34248850, 2021). "Immunohistochemically, the tumor cells were diffuse moderately or strongly positive for CD10, P504S, vimentin, PAX8, RCC, AE1/AE3, and SDHB and focally positive for CK7 and CA IX while negative for cathepsin K, HMB45, Melan-A, Ksp-cadherin, and CD117." (PMID 31828108, 2019). "Importantly, although CLQ suppressed both B16F10 and A375 cell growth in a dose-dependent manner, it did not affect the viability of normal Melan-A and PIG1 melanocytes, suggesting that it is safe for non-tumor cells." (PMID 31138783, 2019). "Singh K showed that the tumor cells are positive for calcitonin, HMB-45, carcinoembryonic antigen (CEA), syn, chromogranin, vimentin, and epithelial membrane antigen and negative for TG, S-100, melan A, and TTF-1." (PMID 30424779, 2018). "The tumor cells are negative for leukocyte common antigen, HMB-45, Melan-A, desmin, and myogenin." (PMID 28143624, 2017). "Tumor cells were negative for PAN-CK, desmin, S-100, melan-A, EMA, and CD10." (PMID 28270196, 2017). "When tumor irrelevant vaccination against the SIV gag was combined with αCTLA-4 i.d., we found a significant increase in TILs from flow cytometry compared to the control and treated animals (no treatment, IgGb2 i.d., and IgGb2, i.d. + Melan-A VLP) without any change in PBMC lymphocytes." (PMID 35406595, 2022). "(Immunohistochemical stains showed that the tumor cells were positive for desmin and TFE3, while negative for pancytokeratin, CAM5.2, EMA, chromogranin, synaptophysin, NSE, CD45, SMA, HHF35, myogenin, CD117, DOG1, MUC4, S100, SOX10, HMB45, Melan-A, CD31, ERG, TLE1, STAT6, and Cathepsin-K)." (PMID 35001360, 2022).
cancer (65 papers, 2002 to 2026). A tumor composed of atypical neoplastic, often pleomorphic cells that invade other tissues. "Controlling the false discovery rate at 5%, ECAR selected six genes CHRM3, CTCFL, KCNE2, MLANA, MSMP, TTLL2, many of which have been reported to be associated with lung function or cancer." (PMID 34857823, 2021). "Several cancer biomarker genes were downregulated following treatment in responders, including MLANA (log2 fold change = − 4.19; p = 0.0617) and MAGEC2 (log2 fold change = − 5.19; p = 0.0308)." (PMID 33407577, 2021). "We loaded ImmDCs and MaDCs from three donors with a mixture of equal amounts of seven long peptides (25–40 mers) from the known cancer associated antigens PMEL, MAGEA4, MLANA, and CTAG1A (NY-ESO1)." (PMID 32983136, 2020). "Accordingly, these CD8+ T cells also shown enhanced cytolytic activity over cancer cells presenting Melan-A." (PMID 33613517, 2020). "MLANA is a target for cancer immunotherapy, such as adoptive T cell therapy and cancer vaccines." (PMID 39611400, 2024). "Regarding Melan A, indicative of the presence of melanin, it was hypothesized that it would correlate with pigmented forms of carcinomas, where small and large gray-blue clumps and fine granularities at the periphery are observed." (PMID 39399171, 2024). "Furthermore, based on the results of this study, the immunodiagnostic MDX cocktail containing antibodies against Melan-A, PNL2, TRP-1, and TRP-2 remains the gold standard for accurately differentiating OMMs from STS and other undifferentiated malignant neoplasms in a routine diagnostic setting." (PMID 34422947, 2021). "In complete responders, skin lesion RNA sequencing after treatment, compared with baseline, identified increased inflammation (CXCL5, CXCL8, IL1A, COL1A1) and downregulated cancer markers (PRAME, S100B, MLANA, STK32A)." (PMID 42316430, 2026). "The biopsy of the nodular lesion revealed an undifferentiated malignant tumor, and immunohistochemical analysis using anti-SOX10, anti-Melan A, and anti-HMB45 antibodies confirmed melanocytic origin." (PMID 41982568, 2026). "To set DCMU doses used in the following experiments, we first tested toxicity of DCMU in CD8+ T cells by evaluating cell viability in a cancer-specific CD8+ T-cell clone (CTL03.1), directed against the melanoma antigen Melan-A." (PMID 35967413, 2022). "Top three mostly used canvaxgens are PMEL, MLANA and CTAG1B, often targeting multiple cancer types." (PMID 38204924, 2024). "In addition to this panel, Melan-A, CDX2, p63, or p40 were added to patients diagnosed with poorly differentiated carcinoma metastasis." (PMID 35308701, 2022). "Specific fields distinguish and classify mutated epitopes (neoepitopes), tumor-associated antigens (TAA) such as differentiation or tissue-specific antigens (e.g., Melan-A, PSA), overexpressed antigens (e.g., HER-2, Muc-1), or cancer-germline antigens (e.g., MAGE, NY-ESO1)." (PMID 34504503, 2021). "Notably, Melan-A failed to stain the neoplastic cells, instead highlighting dendritic melanocytes at the periphery of carcinoma nests." (PMID 41542309, 2026). "Furthermore, our findings extend beyond cancer cell lines to include non-cancer cell lines such as Melan-A cells, providing additional validation of the melanophagy cascade." (PMID 39477686, 2025). "However, clinical findings do not consistently support the use of gp100 and Melan-A/MART-1 TAA vaccines for cancer immunotherapy, as responses are poor and tumor regression is often not achieved." (PMID 35651800, 2022). "We performed immunostaining for transcription factor E3 (TFE3), human melanoma black 45 (HMB45), melan-A, desmin, pan-cytokeratin (CK), paired box 8 (PAX8), CD10, hormone receptors, and S100, and targeted RNA and DNA sequencing using commercially available cancer gene panel." (PMID 35626258, 2022). "The immunophenotype in our case, positivity for HMB-45, Melan-A, and SOX10 with absence of pancytokeratin, confirmed melanocytic lineage while helping to exclude carcinoma." (PMID 40918809, 2025).
cancer (continued). "Furthermore, although the MAGE-1, MAGE-3, Melan-A, gp100, tyrosinase, HER-2, and NY-ESO-1 are expressed in normal testicular, retinal, and/or brain tissues, no autoimmune responses have been elicited in the clinical trials or animal experiments of cancer vaccines." (PMID 25126583, 2014).
infection (9 papers, 2011 to 2025). The state of being infected such as from the introduction of a foreign agent such as serum, vaccine, antigenic substance or organism. "It has also been suggested that infection and surgery elicit an increased host immune response directed against specific melanocyte-associated antigens such as Melan-A." (PMID 34607999, 2021). "Mutation of the mLANA E3L domain abrogates MHV68-driven GC B cell infection, implicating mLANA E3L activity in GC B cell proliferative expansion." (PMID 34586873, 2021). "Nevertheless, NF-κB signaling is likely downregulated during specific phases of infection, as both mLANA and MHV-68 RTA target NF-κB subunit RelA/p65 for degradation." (PMID 34586873, 2021). "MHV68 infection drives immortalization of primary murine fetal liver B cells, and mLANA and v-cyclin both contribute to this process." (PMID 34586873, 2021). "Since kLANA supported episome maintenance of mTR DNA, we asked if kLANA can functionally replace mLANA in MHV68 to support infection in vivo." (PMID 28910389, 2017). "The reduction of titers at day 7 indicates that kLANA cannot fully replace mLANA during lytic replication in vivo, and disruption of kLANA N-terminal chromosome binding or C-terminal DNA binding affected this phase of infection." (PMID 28910389, 2017). "To ensure that our mLANA mutants would express in the context of infection, we infected NIH3T3 cells at an MOI of 3 PFU/cell and collected lysates at seven hours post-infection." (PMID 22969427, 2012). "However, the severe latency establishment defect observed following infection of AIDcre/+ mice is most consistent with a model in which mLANA facilitates viral genome maintenance in rapidly proliferating GC B cells." (PMID 29364981, 2018). "Immunoblots confirmed mLANA or kLANA expression after infection with WT or chimeric viruses." (PMID 28910389, 2017). "kLANA or kLANA mutants distributed similarly to mLANA after infection with the chimeric viruses." (PMID 28910389, 2017). "mLANA likely sets the stage for transformation, by interacting with and altering pro-growth and anti-apoptotic pathways, stabilizing the cell and by turning off lytic genes, preventing the infected FL cells from succumbing to lytic infection." (PMID 21931547, 2011). "During primary infection of fibroblasts, mLANA has been shown to be required for efficient replication of the virus, and in the absence of mLANA, the virus shows dysregulated expression of viral genes and an early hyperlytic phenotype, resulting in a lower output of virus overall." (PMID 21931547, 2011). "To test for such a possibility, we evaluated mice at various stages of infection following inoculation with O73.loxP compared to WT MHV68 and mLANA-null 73.STOP control viruses." (PMID 29364981, 2018). "While WT MHV68 established latency normally, neither O73.loxP nor mLANA-null 73.STOP were detected in the spleens of AIDCre/+ mice on day 16 post-infection." (PMID 29364981, 2018). "The small deficit in lung replication of kLANA chimeric virus suggests that kLANA does not fully replace mLANA in this phase of infection." (PMID 28910389, 2017). "Regardless of the binding modes, both kLANA and mLANA bind to reciprocal DNA, this fuels the idea that it might be feasible to substitute mLANA with kLANA within MHV-68 virus and to explore kLANA function in a mouse model of infection." (PMID 26424851, 2015).
infection (continued). "Furthermore, the absence of a phenotype during acute infection suggests that mLANA expression in B cells is not a major contributor to acute viral replication in the lung." (PMID 29364981, 2018). "However, on day 17 after infection, when MHV-68 latency had been established, the 4A mutant showed a pronounced reduction of viral genome copy numbers in spleen cells approaching the phenotype seen with the mLANA deletion mutant." (PMID 24146614, 2013). "However, an inherent problem with this approach is that the absence of mLANA at early stages of infection may indirectly influence phenotypes observed at subsequent stages." (PMID 29364981, 2018).
MLANA also shares sentences with these, for which no sentence is quoted: lymphoma (5 papers); schwannoma (5); lymphangioleiomyomatosis (4); prostate carcinoma (4); malignant peripheral nerve sheath tumor (3); smooth muscle tumor (3); squamous cell carcinoma (3); undifferentiated pleomorphic sarcoma (3); esophageal squamous cell carcinoma (2); granular cell tumor (2); hepatocellular carcinoma (2); liposarcoma (2); neurothekeoma (2); pheochromocytoma (2); sarcomatoid carcinoma (2); sex cord tumors (2); synovial sarcoma (2); adenocarcinoma (1); adenoid cystic carcinoma (1); alveolar rhabdomyosarcoma (1); angioleiomyoma (1); angiolipoma (1); autoimmune disease (1); Barrett esophagus (1); benign granular cell tumor (1); blue nevus (1); Café-au-lait macule (1); carcinoid tumor (1); colon cancer (1); colorectal carcinoma (1).
A further 41 diseases each share a sentence with MLANA in 1 paper.